APBA1 (amyloid beta precursor protein binding family A member 1)
Description:
Putative function in synaptic vesicle exocytosis by binding to Munc18-1, an essential component of the synaptic vesicle exocytotic machinery. May modulate processing of the amyloid-beta precursor protein (APP) and hence formation of APP-beta. Component of the LIN-10-LIN-2-LIN-7 complex, which associates with the motor protein KIF17 to transport vesicles containing N-methyl-D-aspartate (NMDA) receptor subunit NR2B along microtubules (By similarity).
Synonyms: MINT1; X11; D9S411E; LIN10; X11A; X11ALPHA
Tractability: Small molecule: it has a high-quality binding pocket. Antibody: its Gene Ontology location is reachable by antibodies, with medium confidence. PROTAC: its protein half-life has been measured; a small molecule that binds it is known.
Gene: Protein-coding gene on chromosome 9 (69,427,532 to 69,672,371, reverse strand). Ensembl gene ENSG00000107282.
Subcellular location: Cytoplasm; Cytoplasm, perinuclear region; Nucleus; Golgi apparatus (Isoform 2)
Subcellular location (Human Protein Atlas): Golgi apparatus
Pathways (Reactome):
Neuronal System: Assembly and cell surface presentation of NMDA receptors; Dopamine Neurotransmitter Release Cycle; Neurexins and neuroligins
Gene Ontology:
Molecular function: identical protein binding; protein binding; amyloid-beta binding
Biological process: axo-dendritic transport; cell adhesion; chemical synaptic transmission; intracellular protein transport; nervous system development; protein transport; protein-containing complex assembly
Cellular component: Golgi apparatus; cytoplasm; cytosol; dendritic spine; membrane; plasma membrane; synaptic vesicle; nucleus; perinuclear region of cytoplasm
Genetic constraint (gnomAD): Loss-of-function variants: 50 observed, 64.71 expected, observed/expected ratio (o/e) 0.77, 90% interval 0.62 to 0.98. The upper end of that interval is the gene's LOEUF score, 0.98, which puts it in group 4 of 6, group 1 being the genes least tolerant of losing a copy. Missense variants: 921 observed, 955.31 expected, observed/expected ratio (o/e) 0.96, 90% interval 0.91 to 1.02. Synonymous variants: 434 observed, 394.05 expected, observed/expected ratio (o/e) 1.1, 90% interval 1.02 to 1.19.
Homologues: Orthologues: chimpanzee APBA1 (99% identical), macaque APBA1 (99% identical), dog APBA1 (96% identical), guinea pig APBA1 (96% identical), pig APBA1 (95% identical), rat Apba1 (94% identical), mouse Apba1 (94% identical), tropical clawed frog apba1 (86% identical), zebrafish apba1a (75% identical), Drosophila melanogaster X11Lbeta (40% identical), Caenorhabditis elegans lin-10 (34% identical). Paralogues in human: APBA2 (49% identical), APBA3 (33% identical), SDCBP (10% identical), SDCBP2 (9% identical).
Diseases named in the same sentence as APBA1 in open-access papers:
APBA1 is named in the same sentence as 30 diseases in open-access papers, as found by Europe PMC text mining. Sharing a sentence is not in itself a finding about the gene and the disease. The quoted sentences say what the papers report.
Alzheimer disease (8 papers, 2013 to 2024). A progressive, neurodegenerative disease characterized by loss of function and death of nerve cells in several areas of the brain leading to loss of cognitive function such as memory and language. "APBA1 encodes a neuronal adaptor protein that interacts with amyloid precursor protein, encoded by the Alzheimer disease-associated APP gene." (PMID 38575728, 2024). "Functional over-expression of APBA1/X11-Beta has been shown to decrease the production of amyloid-β, a toxic peptide deposited in Alzheimer's disease brains." (PMID 24367640, 2013). "APBA1/Mint1 was upregulated in the brain tissue of people with Alzheimer’s disease." (PMID 28640909, 2017).
depression (2 papers, 2015). "In conclusion, we originally investigated the relationship of 5-HT6R-serotonin-APBA1/2 between AD and depression, and we suggest a potential mechanism for the network of 5HT6R-serotonin-APBA1/2 in the AD mouse model." (PMID 26449188, 2015). "We suggest that APBA1/2 is novel proteins regulated by 5-HT6R in AD, as well as our data imply the novel function of APBA1/2 via 5-HT6R in depression." (PMID 26449188, 2015). "Although we firstly found that the network of 5-HT6R-Serotonin-APBA1/2 occurs in depression patients by analyzing human depression patients, we are further studying to demonstrate the functional network of 5HT6R-Serotonin-APBA1/2 in a depression mouse model." (PMID 26449188, 2015). "To order to validate the correlation between 5-HT6R and APBA1/2, we analyzed mRNA in depression patients, AD patients, and AD mouse model." (PMID 26449188, 2015). "Thus, it is of interest to find the correlation of APBA1/2 with 5-HT6R in depression patients." (PMID 26449188, 2015). "5-HT6R mRNA was significantly correlated with APBA1 and APBA2 in brain tissues of depression patients." (PMID 26449188, 2015). "We further explored correlation between expression levels of two ABPA genes such as APBA1 and APBA2 and those of serotonin receptors in the hippocampus of individuals with depression and unaffected controls using RNA sequencing data which were deposited in the SNCID." (PMID 26449188, 2015). "We found that APBA1/2 related with amyloid beta A4 precursor protein (APP) metabolism in AD was correlated with 5-HT6R in depression patients, and regulated by 5-HT6R in the AD mouse model, suggesting significant implications for the network of 5-HT6R between AD and depression." (PMID 26449188, 2015).
Obesity (2 papers, 2024 to 2025). Accumulation of substantial excess body fat. "The links identified here with predominantly adult-onset obesity may be consistent with the putative roles of APBA1 and BSN in aging-related neurosecretory vesicle dysfunction and neurodegeneration." (PMID 38575728, 2024). "Rare PTVs in APBA1 and BSN appear to preferentially confer risk of adult-onset obesity, which we propose might be due to widespread dysregulation of neurodevelopment, neurogenesis and neuronal oxidative phosphorylation in neurons within the central feeding circuitry." (PMID 38575728, 2024). "Therefore, APBA1 and BSN appear to be among the few genetic determinants of predominantly adult-onset obesity." (PMID 38575728, 2024). "In contrast to almost all previously reported obesity-associated genes, neither BSN nor APBA1 showed any association with childhood body size or puberty timing (P > 0.05), suggesting adult-onset effects on body weight based on the phenotypes available in UK Biobank." (PMID 38575728, 2024).
glioma (1 paper, 2023). A benign or malignant brain and spinal cord tumor that arises from glial cells (astrocytes, oligodendrocytes, ependymal cells).
sarcoma (1 paper, 2023). A usually aggressive malignant neoplasm of the soft tissue or bone. "Interestingly, overexpression of these regulatory proteins such as CASK, TIAM1, APBA1, and NRXN, have also been linked with sarcoma progression." (PMID 36599925, 2023).
genetic diseases (2 papers, 2012 to 2024). "We identified four high-impact variants in four candidate novel genes (ZBTB38, AQR, APBA1, and TXLNA) not implicated before in NDD or genetic diseases in four probands/families." (PMID 38300321, 2024).
neurodegenerative disease (1 paper, 2010). A disorder of the central nervous system characterized by gradual and progressive loss of neural tissue and neurologic function. "Each region also included key genes associated with addiction (Maoa, Ptprd, and Slit3), psychiatric illnesses (Maoa, Myt1l, Slc12a6, and Slit3), and neurodegenerative diseases (Apba1 and Slc12a6)." (PMID 20808911, 2010).
APBA1 also shares sentences with these, for which no sentence is quoted: tumor (7 papers); adenoma (2); cancer (2); colon cancer (2); colorectal cancer (2); Adult onset (1); chronic heart failure (1); colorectal tumours (1); diabetes (1); dysplasia (1); epilepsy (1); gastric cancer (1); gastric MALT lymphoma (1); heart failure (1); metastasis (1); neurodevelopmental disorder (1); neurological disease (1); Onset (1); psychiatric disorder (1); rectal carcinoid tumors (1); schizophrenia (1); spinocerebellar ataxia (1); type 2 diabetes (1).